LGALS3 (galectin 3)
Diseases named in the same sentence as LGALS3 in open-access papers (continued):
Sharing a sentence is not in itself a finding about the gene and the disease.
schistosomiasis (4 papers, 2009 to 2017). An infectious disease caused by parasitic trematodes of the genus Schistosoma that colonize human blood vessels and release eggs that can cause granulomatous reactions leading to acute (swimmer's itch or acute schistosomiasis syndrome) or chronic disease. "The downmodulation of macrophages in Lgals3-/- infected mice during the first step of the infection could be directly associated with a type of fibrogranulomatous reaction in the liver and, consequently, drive profibrotic events during schistosomiasis." (PMID 28231240, 2017). "Perhaps, galectin-3 has an anti-apoptotic role in lymph node cells in the course of chronic phase of schistosomiasis." (PMID 21573150, 2011). "Here, we suggested a possible involvement of Galectin-3 (Gal-3), histone deacetylases (HDACs), and Hedgehog (Hh) signaling with macrophage activation during Th1/Th2 immune responses, fibrogranuloma reaction, and tissue repair during schistosomiasis." (PMID 28231240, 2017). "Thus, we propose that, at least in part, galectin-3 plays a regulatory role in anti-apoptotic events and/or phagocytosis of dead cells during schistosomiasis." (PMID 21573150, 2011). "During schistosomiasis, both eggs and the adult worms synthesize GalNAcβ1-4(Fucα1-3)GlcNAc(Lac-DiNAc) structures (N-acetylgalactosamine β1-4 N-acetylglucosamine) that interact with galectin-3." (PMID 21573150, 2011). "Together, these data indicate that the lack of galectin-3 disturbs severely B lymphocyte and plasma cell niches during chronic phase of schistosomiasis." (PMID 21573150, 2011).
serous ovarian cancer (4 papers, 2010 to 2021). "This study indicates that with regard to EGFR and cytoplasmic galectin-3 immunoexpression, multiple marker testing may be an adjunct in the identification of high-risk ovarian serous cancers." (PMID 23658855, 2010). "Since we found that Pect‐MCP could modulate integrin expression levels, next we investigate a possible relationship between LGALS3 and integrin mRNA levels in different subtypes of human serous ovarian cancer." (PMID 31197964, 2019).
Sickle Cell Anemia (4 papers, 2016 to 2023). "In this study, cardiac fibrosis and subclinical cardiac changes in children with sickle cell disease were evaluated using cardiac magnetic resonance imaging (MRI), tissue Doppler echocardiography and serum galectin-3." (PMID 37715793, 2023). "In the current study, galectin-3 levels were significantly higher among children with sickle cell disease than among healthy control subjects (P < 0.001)." (PMID 37715793, 2023). "Children with sickle cell disease were divided according to age into two subgroups: subgroup I (age < 13.5 years) and subgroup II (> 13.5 years); galectin-3 levels were significantly higher in the older group (P = 0.01)." (PMID 37715793, 2023). "LGALS3 +191 and +292 with vaso-occlusive crisis and respiratory tract infection in children with sickle cell anemia attended in Hemope Foundation—Recife/Brazil." (PMID 27603703, 2016). "LGALS3 +191 and +292 combined genotype distribution with vaso-occlusive crisis and respiratory tract infection in children with sickle cell anemia attended in Hemope Foundation—Recife/Brazil." (PMID 27603703, 2016). "LGALS3 +191 and +292 diplotype of serum levels with vaso-occlusive crisis and respiratory tract infection in children with sickle cell anemia attended in Hemope Foundation—Recife/Brazil." (PMID 27603703, 2016). "T1 values and extracellular volume abnormalities correlate well with galectin-3 and tissue Doppler echocardiographic-derived left ventricular MPIm, and these tools are recommended for the detection of early subclinical myocardial abnormalities in children with sickle cell disease." (PMID 37715793, 2023).
systolic heart failure (4 papers, 2015 to 2020). Heart failure caused by abnormal myocardial contraction during systole leading to defective cardiac emptying. "Several studies have addressed the prognostic value of Galectin-3 in patients with either systolic heart failure or HFPEF." (PMID 26582585, 2015).
tauopathies (4 papers, 2020 to 2024). "To assess the importance of Gal3 in tauopathies in vivo, we crossed Tau22 mice with Gal3 knockout mice (Tau22/Lgals3–/–)." (PMID 37988169, 2024). "To further delineate the protective role of Gal3 depletion in tauopathy, we analyzed the gene expression profiles of the hippocampi of Tau22/Lgals3–/– mice and corresponding controls using bulk RNA-Seq." (PMID 37988169, 2024).
airway hyperresponsiveness (3 papers, 2013 to 2018). "Galectin-3-deficient mice develop significantly less airway hyperresponsiveness and dermatitis after allergen challenge and a lower TH2 response." (PMID 26488881, 2015).
anaphylaxis (3 papers, 2021 to 2024). An acute hypersensitivity reaction that occurs from exposure to an allergen. "Other protein related with coagulation processes have been found increased in EC-anaphylaxis: PROC, PROS, APOH, Galectin-3 and TSP1." (PMID 34248989, 2021).
Ascites (3 papers, 2017 to 2024). Accumulation of fluid in the peritoneal cavity (between the layers of the peritoneum that lines the abdomen). "Galectin-3 is already elevated in patients with little ascites, but does not further increase in parallel with ascites volume." (PMID 28661458, 2017). "Another possible explanation for the absence of ROS response to Galectin-3 in some HGSC ascites neutrophils is that they might express surface proteins that affect their response to Galectin-3." (PMID 39759523, 2024).
bladder tumor (3 papers, 2017 to 2025). "Interrogation of the TCGA cohort revealed that TSC1 and TSC2 mutant bladder tumors overexpressed LGALS3 versus other bladder tumors." (PMID 28695825, 2017). "For instance, the poly N-acetyllactosamine, the polymers of LacNAc mediated binding of galectin-3 to MHC class I-related chain A (MICA) has been demonstrated to contribute to the survival of bladder tumor cells and prevent the NK-mediated killing of C2GnT-expressing bladder tumor cells." (PMID 31355147, 2019).
calcification (3 papers, 2022 to 2024). Process by which organic tissue becomes hardened by the physiologic deposit of calcium salts. "Lgals3 levels were also significantly increased in patients with calcific aortic valve disease and stimulated calcification in patients with AS." (PMID 39081633, 2024). "Whereas the important role of galectin-3 in arterial calcification, our previous meta-analysis has reported that galectin-3 is likely a predictor for the adverse outcomes in MI patients." (PMID 35685493, 2022). "In this study, we evaluated the role of TXNIP in galectin-3-induced vascular calcification." (PMID 35771146, 2022).
chorioamnionitis (3 papers, 2021 to 2022). A morphologic finding indicating inflammation of the fetal sac membranes. "In line with this, human amniotic epithelium expresses galectin-1, galectin-3, galectin-7 and galectin-8, and galectin-3 is significantly increased in the amniotic epithelium of patients with chorioamnionitis." (PMID 36017312, 2022). "The biological implications of the upregulated galectin-3 expression in chorioamnionitis remain to be elucidated." (PMID 35008499, 2021).
corneal infection (3 papers, 2014 to 2022). A viral or bacterial infectious process affecting the cornea. "Galectin-3 and CK12 were co-expressed in the corneal epithelium, while galectin-3 and CD11b were aggregated near the corneal ulcer." (PMID 35845133, 2022). "Whereas tissue damage in mice leads to reduced galectin-3 expression, injured tissue in patients with active corneal ulceration show a greater galectin-3 immunoreactivity compared to normal subjects." (PMID 30349544, 2018). "Antibodies specific for either the outer core region of P. aeruginosa LPS or for galectin-3 blocked binding of bacteria to cultured human corneal epithelial cells, implicating galectin-3 in corneal infection and development of bacterial keratitis." (PMID 24995007, 2014).
corticotroph adenoma (3 papers, 2019 to 2025). "The lack of galectin-3 expression in corticotroph adenomas can be pathologically diagnostic of SCAs rather than functioning corticotroph adenomas." (PMID 34220707, 2021). "Galectin 3 (LGALS3) has been incriminated, as well, in the development of lactotroph and corticotroph adenomas." (PMID 40299639, 2025).
dementia (3 papers, 2019 to 2024). Loss of intellectual abilities interfering with an individual's social and occupational functions. "This study examines MCP’s impact on neuroinflammation, cognitive function, and its role in galectin-3 inhibition in a dementia model." (PMID 39727960, 2024). "This study shows that MCP, an antigalectin-3 inhibitor, has an ameliorative effect on dementia, supporting research that galectin-3 regulates inflammation and affects cognitive performance through inflammatory activity." (PMID 39727960, 2024).
demyelinating disease (3 papers, 2018 to 2023). A broad group of disorders that affect the myelin sheaths that cover the neurons. "Interestingly, the detrimental effect of monocyte-derived macrophages may be regulated by TGF-β, as it has been shown that TGF-β-deficient monocytes drive fatal demyelinating disease following engraftment in the spinal cord, with strong up-regulation of disease-associated molecules including Lgals3." (PMID 36779012, 2023). "Galectin-3 also promoted oligodendroglia differentiation, contributing to functional recovery following demyelinating disorders." (PMID 31156388, 2019).
dermatitis (3 papers, 2015 to 2022). An inflammatory process affecting the skin. "Idiopathic inflammatory myopathy patients with associated ILD showed elevated levels of serum galectin-3 compared to the healthy controls accompanied by increased galectin-3 expression in the inflammatory cells of interstitial fibrosis, myositis, and dermatitis." (PMID 36272642, 2022). "There has been no report regarding the role of galectin-3 in blister-forming skin disorders such as BP." (PMID 33150039, 2020).
diastolic heart failure (3 papers, 2015 to 2026). Heart failure caused by abnormal myocardial relaxation during diastole leading to defective cardiac filling. "In order to further elucidate the role of Galectin-3 in HFPEF patients, patients from the Taiwan Diastolic Heart Failure Registry (TDHFR) were enrolled and their plasma Galectin-3 levels were correlated with echocardiographic DHF severity." (PMID 26582585, 2015).
dyslipidaemia (3 papers, 2017 to 2021). "Earlier studies have demonstrated a reverse relationship between galectin-3 and HDL-C in serum, what suggests that AIS regulation, in which galectin-3 participates, is possibly associated with dyslipidaemia and inflammatory condition." (PMID 35053194, 2021).
End Stage Liver Disease (3 papers, 2020 to 2025). Final stage of a liver disease when the liver failure is irreversible and LIVER TRANSPLANTATION is needed. "First, if the patients with acute-on-chronic liver failure related to hepatitis B had galectin-3 methylated promoter, they would have shorter survival time, higher 3-month mortality, and higher model for end-stage liver disease (MELD) score." (PMID 34778306, 2021).
endotoxemia (3 papers, 2018 to 2026). "We therefore propose a model in which gut-derived low-grade endotoxemia drives myeloid secretion of Galectin-3, which in turn sustains constitutive LAG3 expression on Treg cells and contributes to Treg cell insufficiency and islet autoimmunity." (PMID 41477833, 2026). "Galectin-3 has an important role in the regulation of various inflammatory conditions including endotoxemia, and airway inflammation." (PMID 29853535, 2018). "Current research indicated that Galectin-3 contributes to diverse physiologic, and pathologic processes including endotoxemia, and airway inflammation through a multitude of complex signaling pathways." (PMID 29853535, 2018). "In the present study, we aimed to show the effects of simvastatin on the oxidative parameters: GR, GSH-Px, superoxide dismutase (SOD) antioxidants, TBARS, and Galectin-3 in lung tissue in endotoxemia." (PMID 29853535, 2018). "We took advantage of galectin-3 (Gal3) knockout mice and found that the absence of Gal3 decreased the mortality rate oflethal endotoxemia in the first 80 h after the administration of LPS, along with a reduction in the tissular damage in several organs measured by electron microscopy." (PMID 35163089, 2022).
epilepsy (3 papers, 2020 to 2023). A brain disorder characterized by episodes of abnormally increased neuronal discharge resulting in transient episodes of sensory or motor neurological dysfunction, or psychic dysfunction. "The role of LGALS3 in epilepsy needs to be further determined." (PMID 33225612, 2020).
esophageal cancer (3 papers, 2015 to 2022). A primary or metastatic malignant neoplasm involving the esophagus. "In the present study, galectin-3 expression in Eca-109 esophageal cancer cells was confirmed and galectin-3 was implicated as a positive regulator of growth, migration and invasion, and antiapoptotic effector." (PMID 25373317, 2015). "Despite the limited diagnostic and prognostic value of galectin-3 in esophageal cancer, Balasubramanian and colleagues included 52 esophageal carcinoma patients in a study that evaluated whether galectin-3 levels in urine could be used to monitor disease status and/or treatment efficacy." (PMID 36497271, 2022). "Compared to healthy controls, urine galectin-3 levels were significantly higher in esophageal cancer patients, most notably in patients with metastatic disease." (PMID 36497271, 2022). "Regarding the functional role of galectin-3 expression in esophageal cancer, Liang and colleagues studied the effect of increased galectin-3 expression on ESCC cell behavior." (PMID 36497271, 2022). "In conclusion, galectin-3 expression was significantly increased in transfected Eca-109 esophageal cancer cells, resulting in enhanced proliferation, migration and invasion, as well as reduced apoptosis." (PMID 25373317, 2015). "This phenomenon indicates that galectin-3 promotes esophageal cancer cell migration and invasion, although confirmation in galectin-3 gene-silenced Eca-109 esophageal cancer cells is required." (PMID 25373317, 2015). "Galectin-3 mRNA was detected in Eca-109, Eca-109/Neo and Eca-109/Gal-3 cells, indicating that the galectin-3 is endogenously expressed in Eca-109 esophageal cancer cells." (PMID 25373317, 2015). "Another group also used immunohistochemical staining to evaluate whether galectin-3 was a prognostic marker for esophageal cancer patients." (PMID 36497271, 2022). "An improved understanding of the role of galectin-3 in esophageal cancer may provide a novel strategy for the diagnosis and prognosis of esophageal cancer, and the development of novel therapeutic regimens." (PMID 25373317, 2015). "Therefore, in the present study, the effect of galectin-3 on the behavior of the Eca-109 esophageal cancer cell line was investigated." (PMID 25373317, 2015). "However, galectin-3 expression in esophageal cancer tissue remains to be confirmed." (PMID 25373317, 2015). "The effects of galectin-3 expression on tumor progression and metastasis in esophageal cancer, which is an aggressive malignancy, have not yet, to the best of our knowledge, been clarified." (PMID 25373317, 2015). "In the present study, a 31-kDa protein band was detected in non-transfected Eca-109 esophageal cancer cells, revealing that galectin-3 is endogenously expressed." (PMID 25373317, 2015). "However, the importance of galectin-3 in Eca-109 human esophageal cancer cells has not yet been elucidated." (PMID 25373317, 2015). "However, to the best of our knowledge, the galectin-3 expression levels in esophageal cancer have not been reported thus far." (PMID 25373317, 2015). "However, in the present study, only the effect of overexpressed galectin-3 on the behavior of human esophageal cancer Eca-109 cells was observed; the effect of a galectin-3-silencing gene on apoptosis in Eca-109 cancer cells has not yet been observed, although this may be analyzed in the future." (PMID 25373317, 2015).
esophageal varices (3 papers, 2021 to 2025). Abnormally dilated veins of the esophagus. "By comparison, the galectin-3 inhibitor can reduce the hepatic venous pressure gradient in patients with esophageal varices." (PMID 34778306, 2021).
fetal growth restriction (3 papers, 2020 to 2024). A fetus that does not grow beyond the 10th percentile of conventionally accepted weight for gestational age. "Regarding fetal growth disturbances, several articles have linked the levels of galectin-3 expression with intrauterine growth restriction, a low birth weight, and the subsequent outcomes of these conditions, such as preterm labor and neurodevelopmental impairment." (PMID 39200778, 2024).
gingivitis (3 papers, 2023 to 2025). A disorder involving inflammation of the gums; may affect surrounding and supporting structures of the teeth. "The highest galectin-3 and galectin-9 levels were observed in the gingivitis group (p < 0.05)." (PMID 37809904, 2023).
glomerulopathy (3 papers, 2013 to 2022). "It binds AGEs, glycated proteins, and lipids formed, among others, in diabetic patients, and galectin-3 knockout mice have accelerated glomerulopathy and higher renal/glomerular AGEs levels, suggesting that galectin-3 is involved in receptor pathways needed for AGE removal in kidneys." (PMID 29950926, 2018).
glomerulosclerosis (3 papers, 2023 to 2025). A hardening of the kidney glomerulus caused by scarring of the blood vessels. "Moreover, LGALS3 knockout mice developed significant glomerular sclerosis, showed greater susceptibility to AGE-induced renal disease, increased levels of AGE and signaling, and altered patterns of AGE-receptors." (PMID 39042141, 2024).
Hyperinsulinemia (3 papers, 2014 to 2023). An increased concentration of insulin in the blood. "Compensatory hyperinsulinemia and increased insulin production, in mice with transgenically enhanced galectin 3 expression, is enough to sustain relatively normal fasting glycemia compared to the control group on HFD but is insufficient after glucose load." (PMID 32117058, 2020). "In mice with transgenically overexpressed galectin 3, fasting glycemia was similar to the WT control group on HFD but with significantly higher compensatory hyperinsulinemia as a consequence of increased activity and insulin production by β cells." (PMID 32117058, 2020).
hypertensive nephropathy (3 papers, 2016 to 2023). Kidney damage that results from chronically elevated blood pressure; complications include glomerular damage resulting in proteinuria and hematuria. "Pharmacological inhibition of galectin-3 attenuates hypertensive nephropathy in rodent models." (PMID 36175599, 2022).
joint diseases (3 papers, 2013 to 2017). "Moreover, its regulatory role in inflammatory bone and joint disorders entitles galectin-3 as a possible therapeutic target." (PMID 29160796, 2017).
left ventricular dilation (3 papers, 2018 to 2023). "We found that cardiac transcripts of established HF plasma biomarkers, including TIMP1 and galectin-3, were differentially expressed in ISO-treated mouse hearts and correlated with left ventricular dilation compared to the control group." (PMID 30201759, 2018).
leiomyosarcoma (3 papers, 2013 to 2021). An uncommon, aggressive malignant smooth muscle neoplasm, usually occurring in post-menopausal women. "Further subgroup analysis within the tumoral group (myomas and leiomyosarcomas) revealed an additional negative correlation between pEGFR Y845 and galectin-3 (gal-3) staining." (PMID 23449029, 2013).